FGFR2 (fibroblast growth factor receptor 2)
Diseases named in the same sentence as FGFR2 in open-access papers (continued):
Sharing a sentence is not in itself a finding about the gene and the disease.
cancer (continued). "The OD-BRE-0438 model with the most resistant phenotype, as evidenced by the shortest median PFS, showed statistically significant upregulated gene expression of FGF1, FGF7, and FGF8 ligands in cancer cells, while FGFR1, FGFR2, or FGFR3 were not upregulated." (PMID 40227585, 2025). "Because the cancer multi-gene panel testing using percutaneous tissue sample revealed MSI-high and TMB-high, whereas no fibroblast growth factor receptor 2 (FGFR2)-related abnormality, he received pembrolizumab monotherapy as second-line therapy." (PMID 40308703, 2025). "R3mab, a FGFR3 (IIIB and IIIc isoforms)-specific monoclonal antibody (does not affect FGFR1, FGFR2, or FGFR4), has been shown to significantly inhibit FGF1-induced cancer cell proliferation." (PMID 29949887, 2018). "Cells measurements confirmed that FGFR2-expressing cells had larger diameters than cells without FGFR2 expression (Figure S4A1, S4A2), further supporting that FGFR2-expressing cells potentially harbor cancer stemness properties." (PMID 27107424, 2016). "For experimental validation, we selected cancer cell lines that harbor amplifications of ERBB2 (OE19) and FGFR2 (HSC39), and used cell lines without these amplifications as controls." (PMID 23737949, 2013). "The limited number of FGFR2-positive CRC patients in our study meant that the relationship between FGFR2 and HER2 status in CRC could not be fully assessed with respect to differences between primary cancer locations and histological types." (PMID 35585358, 2022). "In addition, other cancer types, including KICH, KIRP, TGCT, and THYM, had almost no FGFR2 alterations." (PMID 33968743, 2021). "The calculated copy numbers of FGFR1, FGFR2 and FGFR3 deviated from the normal genotype of blood and normal tissue samples in the majority of the “squamous-like” tumors, indicating the general genomic instability of progressed cancers." (PMID 27669755, 2016). "FGFR2 and FGFR3 were also up-regulated in some of the cancer cells, but not as markedly as FGFR1." (PMID 26201468, 2015). "Interestingly, upregulation of ERBB ligands only mediated resistance in FGFR3 dependent cells and not FGFR1 or FGFR2 dependent lines suggesting mechanisms of resistance may differ according to the FGFR alteration and cancer type." (PMID 35582593, 2019).
adenocarcinoma (19 papers, 2010 to 2024). A common cancer characterized by the presence of malignant glandular cells. "FGFR2 gene amplification acts as an adverse prognostic marker linked with lymph node metastasis and poorly differentiated adenocarcinoma." (PMID 39195304, 2024). "FGFR2 gene amplification acts as an adverse prognostic marker, closely linked with lymph node metastasis, poorly differentiated adenocarcinoma, and reduced survival." (PMID 39195304, 2024). "Almost nothing is known about the heterogeneous distribution of FGFR2-amplified clones in adenocarcinomas of the upper GIT." (PMID 36416959, 2023). "The present study addresses the following questions: (a) How frequently is heterogeneous FGFR2 amplification found in adenocarcinomas of the upper GIT?" (PMID 36416959, 2023). "Most notably, of the twenty-nine adenocarcinomas, FGFR2 gene fusions were specifically enriched in cholangiolocarcinoma (CLC), with 79.3% (23/29) of cases displaying CLC." (PMID 37964396, 2023). "The intratumoral heterogeneity of FGFR2-amplified adenocarcinomas of the upper GIT has been investigated in only a few studies using different methods." (PMID 36416959, 2023). "FGFR2 translocations preferentially occur in iCCA at a frequency of 15%, relative to other adenocarcinomas, creating constitutively active fusions to many different gene partners." (PMID 36479082, 2022). "In this paper, bFGF, FGFR1 and FGFR2 expression was examined in adenocarcinoma and SCC, and high bFGF expression was found to be a good predictor of OS in SCC." (PMID 26824699, 2016). "We examined whether FGFR2 amplification correlates with FGFR2 mRNA and FGFR2 expression in the five kinds of human EGJ adenocarcinoma cell lines, namely OACM5.1C, OE19, OE33, SK-GT-4 and FLO-1." (PMID 26933914, 2016). "Therefore, for investigating the oncogenic effect of FGFR2 in EGJ adenocarcinoma cell lines, we adopted OACM 5.1C and FLO-1 as high and low expressers of FGFR2, respectively." (PMID 26933914, 2016). "We initially focused on patient 29, who had a pT3N0 diffuse subtype adenocarcinoma arising from the gastroesophageal junction with amplification of MET, FGFR2, and CCND1 (eFigure 4A in the Supplement)." (PMID 32338752, 2020). "The effects of FGFR2 inhibition or overexpression on cell proliferation, cell cycle, and apoptosis assays were investigated in EGJ adenocarcinoma cell lines." (PMID 26933914, 2016). "We next investigated whether pan-FGFR inhibitor AZD4547 can therapeutically target the EGJ adenocarcinoma cell line OACM5.1C, which overexpresses FGFR2." (PMID 26933914, 2016). "In total, putative actionable genomic targets (FGFR2, BRAF-V600E, MTOR, NRAS, and KDM6A) were identified in 35% of the cases by OncoKB search, an important finding given the high number of fluent transitions from high-grade IEN to adenocarcinoma at the time of diagnosis (14/17 cases)." (PMID 34205964, 2021).
infection (8 papers, 2015 to 2025). The state of being infected such as from the introduction of a foreign agent such as serum, vaccine, antigenic substance or organism. "Infection with type II Runx2-expressing adenovirus induced Fgfr1, Fgfr2, and Fgfr3 mRNA and their IIIb and IIIc isoform mRNA." (PMID 30202094, 2018). "Further investigation into the impact of each shRNA clone on FGFR2 protein structure and function could help clarify its role during infection." (PMID 38585651, 2024). "Module 2 focused on epithelial barrier function and growth factor signaling, identified EREG, FGFR2, and MET as central hubs, alongside AREG and HBEGF, which support epithelial repair and regeneration after infection-induced damage." (PMID 40634947, 2025). "This is functionally relevant, because activation of FGFR2 signaling in keratinocytes by its canonical ligands FGF7 and FGF10 promoted infection with Herpes Simplex Virus (HSV)-1 or Zika virus, which correlated with reduced expression of ISGs." (PMID 39621133, 2024). "Indeed, we previously showed that treatment of immortalized human HaCaT keratinocytes with AZD4547 and BGJ398, which inhibit the kinase activity of FGFR1, FGFR2 and FGFR3, reduces the infection with HSV-1." (PMID 39621133, 2024). "To test whether reduced protein levels of EPHB4, ERBB2, FGFR2, or IGF1R impacted infection, we infected control and knockdown lines with DENV2 MON601 for 24 h." (PMID 38585651, 2024). "While FGFR2-1 and -3 knockdown lines demonstrated reduced infection, FGFR2-3 did not." (PMID 38585651, 2024).
skeletal dysplasia (8 papers, 2007 to 2025). Any Mendelian diseases that affects growth and development of the skeleton. "Skeletal dysplasia (SD) is one of the most common inherited neonatal disorders worldwide, where the recurrent pathogenic mutations in the FGFR2, FGFR3, COL1A1, COL1A2 and COL2A1 genes are frequently reported in both non-lethal and lethal SD." (PMID 34789231, 2021). "The described FGFR1 and FGFR2 mutations occur outside the kinase domain, but in identical positions to activating germline mutations known to predispose to skeletal dysplasias." (PMID 17487277, 2007).
genetic disease (6 papers, 2012 to 2025). "However, many mammalian genes involved in genetic disease, particularly signaling receptors such as FGFR2 (120 kilobases) and structural proteins such as dystrophin are significantly larger than 10 kilobases." (PMID 32013077, 2020).
cardiac diseases (2 papers, 2020 to 2021).
CNS tumors (2 papers, 2023 to 2024). "Concerning FGFR, all cases displayed FGFR1 hotspot substitutions N546K/D (73%, 27/37) and/or K656E/M (23%, 11/37) preferentially occurring in CNS tumours, but neither FGFR1 fusion/duplication nor FGFR2/3 alterations." (PMID 38066305, 2023).
kidney (2 papers, 2017 to 2022). "In lung malignancies, and specifically LUAD, we have previously shown that the membrane receptor, fibroblast growth factor receptor 2 (FGFR2), is a critical driver of disease progression, especially under non-stimulated conditions." (PMID 29038531, 2017).
neurodevelopmental disorder (2 papers, 2017 to 2023). A behavioral and cognitive disorder with onset during the developmental period that involves impaired or aberrant development of intellectual, motor, or social functions. "Our findings provide new insights into the potential causative role of FGFR2 gene in complex neurodevelopmental disorders." (PMID 37733178, 2023). "Recently, FGFR2 has been hypothesized to be implicated in neurodevelopmental disorders as well." (PMID 37733178, 2023).
benign tumors (1 paper, 2024). "A significantly higher mean percentage of FGFR2-positive expression was found in malignant, precancerous, and benign tumors compared to normal histology (p < 0.001, p = 0.002, and p = 0.008, respectively)." (PMID 39063983, 2024). "The mean percentage of FGFR2-positive expression in benign tumors was found to be similar to that observed in precancerous tumors (p = 0.743)." (PMID 39063983, 2024).
hematologic cancers (1 paper, 2025). "FGFR2 phosphorylation and expression in HCC-827 and Jurkat may reflect signaling plasticity or unexplored functional roles in lung and hematologic cancers." (PMID 41035678, 2025).
kidney disease (1 paper, 2016). "This example, together with Fgfr2, suggests that coordinated functions of other Esrp‐regulated genes may collectively contribute to kidney formation, and that disruption in the expression or splicing of other target genes may also be involved in kidney disease." (PMID 27404344, 2016).
FGFR2 also shares sentences with these, for which no sentence is quoted: craniosynostosis syndromes (25 papers); lymphoid neoplasm (6); Costello syndrome (5); Beare-Stevenson cutis gyrata syndrome (4); head and neck cancer (4); prostate adenocarcinoma (4); thanatophoric dysplasia (4); Kallmann syndrome (3); metabolic disorders (3); neuroendocrine tumors (3); neurofibromatosis (3); Noonan syndrome (3); renal cell carcinoma (3); schizophrenia (3); tooth agenesis (3); acrocephalosyndactyly (2); Barrett esophagus (2); basal cell carcinoma (2); Bent bone dysplasia syndrome (2); cardiovascular disease (2); colitis (2); Crohn disease (2); dermatofibroma (2); dysplasia (2); extraventricular neurocytoma (2); gastrointestinal tumors (2); Hartsfield syndrome (2); Hearing impairment (2); heart failure (2); hyperplasia (2).
A further 187 diseases each share a sentence with FGFR2 in 2 papers or fewer.